TRPV3 (transient receptor potential cation channel subfamily V member 3)
Diseases named in the same sentence as TRPV3 in open-access papers (continued):
Sharing a sentence is not in itself a finding about the gene and the disease.
Insulin resistance (1 paper, 2023). Increased resistance towards insulin, that is, diminished effectiveness of insulin in reducing blood glucose levels. "Of the 166 GDM women followed up postpartum, rs62069863 in TRPV3 gene was positively associated with fasting insulin, homoeostasis model assessment of insulin resistance." (PMID 38087213, 2023). "TRPV3 was associated with worse insulin resistance postpartum." (PMID 38087213, 2023). "Further, we found that TRPV3 was positively related with worse insulin resistance of GDM women during the postpartum period." (PMID 38087213, 2023). "Further, our results showed a significant correlation between TRPV3 and insulin resistance in GDM women after delivery." (PMID 38087213, 2023). "Further, our data indicated that TRPV3 might participate in insulin resistance in GDM women postpartum." (PMID 38087213, 2023).
irritation (1 paper, 2021). "Moreover, activation of TRPV3 by α-hydroxyl acid–containing compounds causes excessive KC exfoliation that is linked with skin irritation, and ablation of TRPV3 attenuated skin lesions in mice." (PMID 34909715, 2021).
keratinization disorders (1 paper, 2012). "Studies have suggested that TRPV3 plays a role in skin keratinization, hair growth, and possibility itching sensation in humans and selectively targeting TRPV3 could provide therapeutic potential for keratinization disorders." (PMID 23320205, 2012).
liver disease (1 paper, 2025). "Interestingly, many of the genes linked to the differentially methylated CpGs have been associated with liver disease progression (eg, DCP2, TRPV3, ARRB1, KCNIP4, MIR10A) and cancer formation or progression (eg, MTHFR, GRIK2, GSN, HOX3, KCNMA1)." (PMID 40275933, 2025).
liver fibrosis (1 paper, 2023). "To conclude, the upregulation of TRPM7, TRPM8, TRPV3, TRPV4, and TRPC6 is significantly associated with the onset and progression of liver fibrosis." (PMID 37569884, 2023). "Similarly, drofenine, a TRPV3 selective agonist, exacerbated liver fibrosis in a CCl4-induced mouse liver fibrosis model, while forsythoside B, a TRPV3 inhibitor, significantly mitigated liver fibrosis, although the underlying mechanism warrants further investigation." (PMID 37569884, 2023). "In the context of liver fibrosis, the upregulation of TRPC6, TRPV3, TRPV4, and TRPM7 channels promotes the activation of HSCs and the production and accumulation of ECM components, including α-SMA and COL1A1." (PMID 37569884, 2023).
Myocardial fibrosis (1 paper, 2025). "Therefore, these preliminary findings suggest that TRPV3 might play a role in myocardial fibrosis, although they need to be confirmed using TRPV3 KO mice." (PMID 40149710, 2025). "Emerging evidence suggests that TRPV1, TRPV3, and TRPV4 channels play a crucial role in myocardial fibrosis." (PMID 40149710, 2025).
small cell lung carcinoma (1 paper, 2025). Small cell lung cancer (SCLC) is a highly aggressive malignant neoplasm, accounting for 10-15% of lung cancer cases, characterized byrapid growth, and early metastasis. "Furthermore, TRPV3 opening enhances the vascular endothelial growth factor signaling in non–small cell lung cancer cells, suggesting a promoting role of TRPV3 in angiogenesis." (PMID 41240425, 2025).
urothelial carcinoma (1 paper, 2025). A malignant neoplasm derived from the transitional epithelium of the urinary tract (urinary bladder, ureter, urethra, or renal pelvis). "Collectively, these findings support further investigation of TRPV3 as a potential pharmacological target and exploratory biomarker in urothelial carcinoma." (PMID 41422779, 2025).
cancer (15 papers, 2020 to 2025). A tumor composed of atypical neoplastic, often pleomorphic cells that invade other tissues. "Several top-ranking IP genes were found in multiple cancer types, including ACCN2, GRIN2D, and TRPV3 that associated with poor prognosis in six cancer types, and P2RX6 in seven cancer types." (PMID 38177502, 2024). "An increased TRPV3 expression has been associated with cancer cell proliferation, survival, and invasion." (PMID 37892239, 2023). "Additionally, TRPV3 activation can induce the expressions of genes associated with cancer progression and metastasis, including matrix metalloproteinases (MMPs) and VEGF." (PMID 37892239, 2023). "TRPC4, TRPV2, TRPV1, and TRPV3 loss variations were found in nearly all cancers." (PMID 35831825, 2022). "TRPV3 activation in these cells triggers ATP release, a signal potentially promoting cancer progression." (PMID 41422779, 2025). "Among them, TRPV3 (Transient receptor potential vanilloid 3) is a member of the vanilloid subfamily and has become a new target for cancer treatment interventions." (PMID 38706904, 2024). "Transient receptor potential vanillin 3 (TRPV3) has been preliminarily discovered to play an important role in various cancers, including BC." (PMID 38706904, 2024). "Several studies have reported altered expression patterns of TRPV3 in various cancer types, indicating its possible involvement in oncogenic processes." (PMID 37892239, 2023). "In some cancers, such as non-small lung cancer, melanoma, squamous cell carcinoma, and breast cancer, TRPV3 expression has been found to be upregulated." (PMID 37892239, 2023). "The activation of TRPV3 has been shown to promote cancer cell growth by triggering the intracellular signaling pathways involved in cell proliferation, such as the ERK1/2 pathway." (PMID 37892239, 2023). "The overexpression of TRPV3 has been found in skin pain, breast pain, cancer pain and other pain tissues." (PMID 36677834, 2023). "For example, TRPA1, TRPC1, TRPV4, TRPV5, and TRPV6 exhibited higher CNV amplification, while TRPV1, TRPV2, TRPV3, and TRPC3 exhibited frequent CNV loss in cancer." (PMID 35614079, 2022). "As TRPV3 is present in the same signaling complex with EGFR and EGFR activity triggers TRPV3, there is a clear functional interplay in between these factors and it potentially plays a role along cancer progression." (PMID 34356643, 2021). "However, it is undeniable that, in addition to our findings, the effect of TRPV3 on cancer also mediated by multiple molecular signaling pathways." (PMID 38706904, 2024). "In general, TRPV3 expression varies across different cancers." (PMID 36677834, 2023). "High TRPV3 levels were detected in 68% of the cancer cases tested (65 out of 96 patients)." (PMID 37240443, 2023). "Studies have shown that TRPV3 may increase the Ca2+ concentration in cancer cells, activate calmodulin kinase, and then, it may affect the cell cycle and promote cell proliferation." (PMID 36677834, 2023). "Furthermore, DNA methylation levels of TRPV3 was further reduced in patients with nodal metastasis, advanced tumor grade, and higher cancer stages." (PMID 35558077, 2022). "Next, we attempted to uncover the upstream regulatory structure of TRPV3 in ccRCC cancer." (PMID 35558077, 2022). "Importantly, TRPV3 expression inversely correlated with cancer differentiation." (PMID 37240443, 2023). "This may also explain why the overexpression of TRPV3 has been detected in many cancer cells." (PMID 36677834, 2023). "TRPV3 and TRPV5 were hypomethylated in most cancer types, while TRPV4 was hypermethylated (P <0.05)." (PMID 35174089, 2022). "For example, TRPV5 and TRPV6 were down-regulated in most cancers, while TRPV2 and TRPV3 tend to be up-regulated in most cases." (PMID 35174089, 2022). "TRPV1 in KIRC, TRPV2 in LUSC, TRPV3 in BRCA, TRPV6 in LUAD and BRCA, while TRPV4 in KIRC and BRCA differed significantly across different cancer subtypes (P <0.05)." (PMID 35174089, 2022).
cancer (continued). "Although the role of TRPV3 in cancer has not been extensively studied, emerging evidence suggests its potential implications in cancer development and progression." (PMID 37892239, 2023). "As a Ca2+-permeable nonselective cation channel, TRPV3 can recognize thermal stimulation (31–39 °C), and it plays an important regulatory role in temperature perception, pain transduction, skin physiology, inflammation, cancer and other diseases." (PMID 36677834, 2023).
tumor (11 papers, 2016 to 2025). "Overactive TRPV3 caused by its gain-of-mutations or skin sensitizers is implicated in skin diseases." (PMID 38154600, 2023). "After that, we assessed the association between TRPV3 expression and the levels of tumor-infiltrating immune cells (TIICs) and immune checkpoints expression." (PMID 35558077, 2022). "In addition, TRPV3 expression was significantly associated with the accumulation of several tumor-infiltrating immune cells, especially regulatory T cells." (PMID 35558077, 2022). "Besides, TRPV3 exhibit a reduction of DNA methylation level with tumor progression, and 12 CpGs of TRPV3 were associated with a significant prognosis." (PMID 35558077, 2022). "Here, we report that echinacoside ameliorates UVB-induced skin damage by directly acting on the Ca2+-permeable and thermosensitive transient receptor potential vanilloid 3 (TRPV3) channel." (PMID 40363831, 2025). "Correlation analysis showed that TRPV3 expression was significant with the accumulation of several tumor-infiltrating immune cells, especially Treg cells (r=0.31, p<0.001)." (PMID 35558077, 2022). "The results showed that TRPV2 and TRPV3 were upregulated in ccRCC tumor tissues, whereas TRPV5 and TRPV6 were downregulated in tumor tissues." (PMID 35558077, 2022). "In summary, this study reveals a new mechanism of the anti-tumor effect of TRPV3 siRNA, which may be a potential therapeutic drug for BC treatment." (PMID 38706904, 2024). "Besides, the promoter methylation level of TRPV3 was significantly lower in ccRCC tissues compared to normal tissues, and the methylation level was further reduced with tumor progression and metastasis progress." (PMID 35558077, 2022). "Therefore, we evaluated the effect of TRPV3 expression on the proportion of tumor-infiltrating immune cells (TIICs) in ccRCC." (PMID 35558077, 2022). "In addition, they found that TSP-1 promotes cell migration by mediating TRPV3 and, in patients, TSP-1 mRNA level in tumor tissue was significantly associated with PSA relapse." (PMID 32600280, 2020). "Single-cell RNA sequencing showed that TRPV3 was expressed in exhausted CD8+ T cells, supporting the model’s relevance to tumor immunity and patient prognosis." (PMID 41331166, 2025). "Given that TRPV3 might play a crucial regulatory role in the differentiation and activation of immune cells, we further explored the correlation between TRPV overexpression and tumor-infiltrating immune cells (TIICs) in ccRCC microenvironment." (PMID 35558077, 2022).
cardiovascular diseases (3 papers, 2019 to 2023). "The current results fully demonstrated that TRPV3 may play a certain role in the occurrence and development of cardiovascular diseases." (PMID 36677834, 2023). "TRPV3 has been found to be a key regulator of cardiovascular diseases." (PMID 33470394, 2021). "Interestingly, we found that TRPV3 was predicted to be one of the target genes of miR-369, and which is an important regulatory gene for cardiovascular disease." (PMID 33470394, 2021).
cardiac diseases (2 papers, 2023 to 2024). "Studies have identified TRPV3 as a key regulator of cardiac diseases." (PMID 36677834, 2023). "There are no TRPV3 antagonists in the current clinical trials, but there is evidence that TRPV3 may be a new direction for the treatment of cardiac diseases." (PMID 36677834, 2023).
peripheral neuropathy (2 papers, 2019 to 2025). A disorder affecting the peripheral nervous system. "The role of Trpv3 is not well understood in peripheral neuropathy though its expression has been reported in mouse peripheral nervous systems and the mRNA exhibited high expression levels in rat DRG in spared nerve injury models of neuropathic pain." (PMID 31652890, 2019). "This process could lead to an accumulation of inflammatory factors at the site due to increased TRPV3 expression, potentially contributing to peripheral neuropathy." (PMID 39926429, 2025).
TRPV3 also shares sentences with these, for which no sentence is quoted: acne (4 papers); rosacea (4); diabetic neuropathy (2); eczema (2); glioma (2); hypertrophy (2); Intellectual disability (2); Allergy (1); Alzheimer disease (1); amyotrophic lateral sclerosis (1); bone cancer (1); cardiomyopathy (1); chronic pancreatitis (1); Cirrhosis (1); Cluster headache (1); colorectal tumor (1); dementia (1); diabetes (1); diffuse palmoplantar keratoderma (1); dry eye (1); Erythema (1); familial hemiplegic migraine types 2 (1); focal palmoplantar keratoderma (1); genetic disorders (1); glioblastoma (1); Hearing impairment (1); Huntington disease (1); Hypothermia (1); integumentary diseases (1); irritable bowel syndrome (1).
A further 14 diseases each share a sentence with TRPV3 in 1 paper.